NME8 (NME/NM23 family member 8)
Description:
Possesses an intrinsic kinase activity. In vitro, does not exhibit nucleoside diphosphate kinase (NDPK) activity or disulfide bond-reducing activity. Additionally, exhibits a 3'-5'-DNA exonuclease activity that removes single nucleotides from the 3' terminus of single-stranded DNA substrates and digests overhanging mismatched 3' termini from double-stranded DNA substrates, suggesting a role in DNA nucleolytic processing. May be required during the final stages of sperm tail maturation in the testis and/or epididymis, where extensive disulfide bonding of fibrous sheath (FS) proteins occurs (By similarity).
Synonyms: NDK8; Sptrx-2; SPTRX2; TXNDC3; CILD6; NM23-H8; DNAI8; HEL-S-99
Tractability: No criterion of Open Targets' tractability assessment is met for any kind of drug.
Gene: Protein-coding gene on chromosome 7 (37,848,597 to 37,900,397, forward strand). Ensembl gene ENSG00000086288.
Subcellular location: Cytoplasm
Subcellular location (Human Protein Atlas): Cytosol; Nuclear speckles; Nucleoplasm; Primary cilium
Gene Ontology:
Molecular function: 3'-5'-DNA exonuclease activity; microtubule binding
Biological process: cilium assembly; DNA catabolic process; flagellated sperm motility
Cellular component: cytoplasm; cytosol; nucleus; outer dynein arm; sperm midpiece; sperm principal piece; axoneme; sperm cytoplasmic droplet; sperm flagellum
Genetic constraint (gnomAD): Loss-of-function variants: 43 observed, 51.41 expected, observed/expected ratio (o/e) 0.84, 90% interval 0.65 to 1.08. The upper end of that interval is the gene's LOEUF score, 1.08, which puts it in group 4 of 6, group 1 being the genes least tolerant of losing a copy. Missense variants: 561 observed, 561.13 expected, observed/expected ratio (o/e) 1, 90% interval 0.93 to 1.07. Synonymous variants: 208 observed, 189.86 expected, observed/expected ratio (o/e) 1.1, 90% interval 0.98 to 1.23.
Gene-disease validity (ClinGen):
ClinGen rates the evidence that NME8 causes each of these diseases.
primary ciliary dyskinesia (autosomal recessive): Disputed. A rare, genetically heterogeneous, primarily respiratory disorder characterized by chronic upper and lower respiratory tract disease.
Homologues: Orthologues: chimpanzee NME8 (97% identical), macaque NME8 (91% identical), pig NME8 (66% identical), dog NME8 (65% identical), mouse Nme8 (63% identical), guinea pig NME8 (62% identical), rat Nme8 (61% identical). Paralogues in human: NME9 (19% identical), NME7 (17% identical), NME5 (13% identical), NME6 (9% identical), NME3 (8% identical), NME4 (8% identical), NME2 (7% identical), NME1 (7% identical).
Diseases named in the same sentence as NME8 in open-access papers:
NME8 is named in the same sentence as 22 diseases in open-access papers, as found by Europe PMC text mining. Sharing a sentence is not in itself a finding about the gene and the disease. The quoted sentences say what the papers report.
primary ciliary dyskinesia (4 papers, 2014 to 2024). "Nme8, encodes an axoneme protein, and mutations in the Nme8 gene have been implicated to cause primary ciliary dyskinesia." (PMID 34791189, 2022). "Defects in NME8 (aka TXNDC3) have been associated with primary ciliary dyskinesia, and variation in this gene has been linked to increased bone mineral density and knee osteoarthritis risk." (PMID 24829845, 2014). "NME8, a member of the NM23 family, has been identified as a cause of primary ciliary dyskinesia (PCD)." (PMID 38473892, 2024). "Nme8 is a very interesting gene to come up during this analysis, because of its relation to primary ciliary dyskinesia." (PMID 34791189, 2022).
Alzheimer disease (2 papers, 2014 to 2017). A progressive, neurodegenerative disease characterized by loss of function and death of nerve cells in several areas of the brain leading to loss of cognitive function such as memory and language. "Recently, a large meta-analysis of five genome wide association studies (GWAS) identified a novel locus (rs2718058) adjacent to NME8 that played a preventive role in Alzheimer's disease (AD)." (PMID 25486118, 2014).
ciliopathy (2 papers, 2020 to 2022). A genetic disorder of the cellular cilia or the cilia anchoring structures, the basal bodies, or of ciliary function. "CFAP54, NME8, and CFAP46 are ciliopathy-related genes that strongly increase the risk of respiratory infections due to the inability to remove inhaled pathogens, including SARS-CoV-2." (PMID 36552859, 2022). "Three Nme proteins have been implicated in motile cilia function, including Nme8, which is orthologous to the LC3 ODA subunit in Chlamydomonas and has been implicated in human motile ciliopathy." (PMID 33263282, 2020).
diffuse large B-cell lymphoma (2 papers, 2023). "NME/NM23 family member 8 (NME8) has been identified as a predisposition variant in breast cancer and a prognostic marker in diffuse large B-cell lymphoma." (PMID 38283355, 2023).
Infertility (2 papers, 2023). "Some genes with lower expression levels, namely DPCD, NME8, and ENKUR, had not yet been clearly related to biological functions in sperm production, function, and/or infertility-related manifestations." (PMID 37174638, 2023).
diabetic retinopathy (1 paper, 2022). "The analysis of genes in TRD regions suggests the potential distortion of protein–protein interactions influencing obesity and diabetic retinopathy as a result of disadvantageous combinations of allelic variants in Aass, Pgx6, and Nme8." (PMID 34791189, 2022).
mental deficiency (1 paper, 2014). "The involvement of NME8 in neurodegenerative diseases with mental deficiency such as AD has not been reported neither." (PMID 25486118, 2014).
cancer (3 papers, 2019 to 2022). A tumor composed of atypical neoplastic, often pleomorphic cells that invade other tissues. "NME8 is the first metastasis suppressor protein found to be capable of suppressing metastasis of cancer cells without affecting primary tumor growth." (PMID 36761693, 2022).
tumor (2 papers, 2022 to 2023). "The expression of NME8 was negatively correlated with the activity of most tumor marker pathways." (PMID 38283355, 2023).
neurodegenerative disease (1 paper, 2014). A disorder of the central nervous system characterized by gradual and progressive loss of neural tissue and neurologic function. "Although the relationship between NME8 and neurodegenerative diseases had not been well reported, proteins encoded by its family members had been reported to be associated with neurodegenerative disease in two papers." (PMID 25486118, 2014).
NME8 also shares sentences with these, for which no sentence is quoted: knee osteoarthritis (2 papers); Bardet-Biedl syndrome (1); breast carcinoma (1); diaphanospondylodysostosis (1); Ehlers-Danlos syndrome (1); Hydrocephalus (1); lymphoma (1); metastatic melanoma (1); metastatic tumors (1); Obesity (1); Pyle disease (1); respiratory infections (1).